STK11IP (serine/threonine kinase 11 interacting protein)
Description:
May regulate STK11/LKB1 function by controlling its subcellular localization.
Synonyms: KIAA1898; LIP1; LKB1IP; STK11IP1
Tractability: Antibody: its Gene Ontology location is reachable by antibodies, with high confidence. PROTAC: ubiquitination databases record sites on it; its protein half-life has been measured.
Gene: Protein-coding gene on chromosome 2 (219,595,805 to 219,616,452, forward strand). Ensembl gene ENSG00000144589.
Subcellular location: Cytoplasm
Subcellular location (Human Protein Atlas): Vesicles
Pathways (Reactome):
Immune System: Neutrophil degranulation
Gene Ontology:
Molecular function: protein kinase binding; protein sequestering activity
Biological process: intracellular protein localization
Cellular component: cytoplasm; lysosomal membrane; azurophil granule lumen; extracellular region
Genetic constraint (gnomAD): Loss-of-function variants: 102 observed, 120.01 expected, observed/expected ratio (o/e) 0.85, 90% interval 0.72 to 1. The upper end of that interval is the gene's LOEUF score, 1, which puts it in group 4 of 6, group 1 being the genes least tolerant of losing a copy. Missense variants: 1,315 observed, 1,353.8 expected, observed/expected ratio (o/e) 0.97, 90% interval 0.93 to 1.02. Synonymous variants: 557 observed, 559.61 expected, observed/expected ratio (o/e) 1, 90% interval 0.93 to 1.07.
Homologues: Orthologues: chimpanzee STK11IP (99% identical), macaque STK11IP (91% identical), pig STK11IP (79% identical), dog STK11IP (78% identical), guinea pig STK11IP (76% identical), mouse Stk11ip (75% identical), rat Stk11ip (75% identical), tropical clawed frog stk11ip (35% identical), zebrafish stk11ip (35% identical), Drosophila melanogaster CG9044 (24% identical). Paralogues in human: NISCH (21% identical).
Diseases named in the same sentence as STK11IP in open-access papers:
STK11IP is named in the same sentence as 13 diseases in open-access papers, as found by Europe PMC text mining. Sharing a sentence is not in itself a finding about the gene and the disease. The quoted sentences say what the papers report.
Alzheimer disease (1 paper, 2022). A progressive, neurodegenerative disease characterized by loss of function and death of nerve cells in several areas of the brain leading to loss of cognitive function such as memory and language. "Because autophagy also plays a critical role in neurodegenerative diseases, we also searched public databases and found that STK11IP expression is upregulated during the progression of neurodegenerative diseases, including Parkinson’s disease and Alzheimer’s disease." (PMID 35365663, 2022).
Cowden syndrome (1 paper, 2019). "It is also interesting to highlight candidate genes involved in hereditary cancer (BRCA2, BLM, ERCC2, SMARCA4) or connected to inherited CRC, such as Cowden syndrome (SEC23B) and Peutz–Jeghers syndrome (STK11IP)." (PMID 30871259, 2019).
dementia (1 paper, 2024). Loss of intellectual abilities interfering with an individual's social and occupational functions.
melanoma (1 paper, 2020). A malignant, usually aggressive tumor composed of atypical, neoplastic melanocytes. "For each of the genes, namely ZNFx1, RHPN2, STK11IP and UNC45A, from 1 to 3 siRNAs were designed and tested in melanoma cell line A375." (PMID 33041669, 2020). "Here we present the results of transient siRNA-mediated knockdown of the four of such genes, namely, UNC45A, STK11IP, RHPN2 and ZNFX1, in melanoma cell line A375, then assayed the cells for their viability, proliferation and ability to migrate in vitro." (PMID 33041669, 2020). "If the effects of a product of STK11IP antagonize that of LKB1, than the lack of STK11IP mutations in melanoma cells may be expected." (PMID 33041669, 2020). "While the function of STK11IP at the level of the whole body may not be relevant to the melanoma cell model in vitro, the observed pro-migratory effects of STK11IP knockdown align with a tumor suppressor and anti-metastatic function of its major protein partner, LKB1." (PMID 33041669, 2020).
nonalcoholic steatohepatitis (1 paper, 2022). "Mice with STK11IP knockout have increased autophagy levels and are protected against MCD diet- or fasting-induced nonalcoholic steatohepatitis (NASH)." (PMID 35365663, 2022).
cancer (4 papers, 2018 to 2024). A tumor composed of atypical neoplastic, often pleomorphic cells that invade other tissues. "Proteomic techniques have pinpointed specific proteins like lysosomal-associated membrane protein 2 (LAMP2A) and serine/threonine kinase 11 interacting protein (STK11IP), crucial for regulating lysosomal targeting and mTORC1 signaling in diseases such as cancer." (PMID 39199310, 2024). "Specifically, we analyzed the role of five lncRNAs (BBC3, STK11IP, XIST, FDFT1, and PRR14), which are known to be related to cell growth and apoptosis in cancer development." (PMID 34295808, 2021). "Some of them were previously demonstrated to play a role in other cancers (UNC45A, STK11IP), and some were not yet characterized (RHPN2 and ZNFX1)." (PMID 33041669, 2020).
STK11IP also shares sentences with these, for which no sentence is quoted: tumor (4 papers); cardiac hypertrophy (1); heart failure (1); hereditary cancer (1); lung carcinoma (1); neurodegenerative disease (1); Parkinson disease (1).